DNAJA3 (DnaJ heat shock protein family (Hsp40) member A3)
Description:
Modulates apoptotic signal transduction or effector structures within the mitochondrial matrix. Affect cytochrome C release from the mitochondria and caspase 3 activation, but not caspase 8 activation. Isoform 1 increases apoptosis triggered by both TNF and the DNA-damaging agent mytomycin C; in sharp contrast, isoform 2 suppresses apoptosis. Can modulate IFN-gamma-mediated transcriptional activity. Isoform 2 may play a role in neuromuscular junction development as an effector of the MUSK signaling pathway.
Synonyms: hTid-1; HCA57; TID1; Tid1-S; Tid1-L
Tractability: Antibody: UniProt places it where antibodies can reach, with medium confidence; its Gene Ontology location is reachable by antibodies, with medium confidence. PROTAC: ubiquitination databases record sites on it; its protein half-life has been measured.
Gene: Protein-coding gene on chromosome 16 (4,425,805 to 4,456,775, forward strand). Ensembl gene ENSG00000103423.
Subcellular location: Mitochondrion matrix; Cytoplasm, cytosol; Postsynaptic cell membrane
Subcellular location (Human Protein Atlas): Mitochondria; Vesicles
Gene Ontology:
Molecular function: ATP-dependent protein folding chaperone; protein binding; protein kinase binding; ATP binding; heat shock protein binding; Hsp70 protein binding; signaling receptor binding
Biological process: negative regulation of cell population proliferation; negative regulation of transcription by RNA polymerase II; mitochondrion organization; skeletal muscle acetylcholine-gated channel clustering; immune system process; negative regulation of programmed cell death; neuromuscular junction development; protein folding; regulation of cell population proliferation; regulation of immune system process; response to heat; response to stress
Cellular component: actin filament; mitochondrial matrix; mitochondrion; cytoplasmic side of plasma membrane; neuromuscular junction; postsynaptic membrane; cytosol; nucleus
Genetic constraint (gnomAD): Loss-of-function variants: 27 observed, 50.5 expected, observed/expected ratio (o/e) 0.53, 90% interval 0.39 to 0.74. The synonymous counts are far from expectation, so gnomAD's model fits this gene poorly and the ratio says little. Missense variants: 685 observed, 630.65 expected, observed/expected ratio (o/e) 1.09, 90% interval 1.02 to 1.16. Synonymous variants: 292 observed, 240.98 expected, observed/expected ratio (o/e) 1.21, 90% interval 1.1 to 1.34.
Homologues: Orthologues: chimpanzee DNAJA3 (99% identical), macaque DNAJA3 (96% identical), guinea pig DNAJA3 (90% identical), pig DNAJA3 (88% identical), mouse Dnaja3 (88% identical), rat Dnaja3 (88% identical), dog DNAJA3 (84% identical), tropical clawed frog dnaja3 (68% identical), zebrafish dnaja3a (61% identical), zebrafish dnaja3b (60% identical), Drosophila melanogaster CG5504 (46% identical), Caenorhabditis elegans dnj-10 (38% identical). Paralogues in human: DNAJA2 (24% identical), DNAJA1 (24% identical), DNAJA4 (23% identical).
Diseases named in the same sentence as DNAJA3 in open-access papers:
DNAJA3 is named in the same sentence as 59 diseases in open-access papers, as found by Europe PMC text mining. Sharing a sentence is not in itself a finding about the gene and the disease. The quoted sentences say what the papers report.
breast carcinoma (11 papers, 2010 to 2024). "A positive association between the genetically predicted levels of the LSP1 protein and breast cancer risk was observed (p value of 3.63 × 10–5), while DNAJA3 showed an inverse association with breast cancer risk, with a p value of 9.15 × 10–5." (PMID 39468330, 2024). "For the remaining two proteins, LSP1 and DNAJA3, the corresponding genes were in previously GWAS-identified breast cancer risk loci." (PMID 39468330, 2024). "The corresponding genes for the remaining two proteins, LSP1 and DNAJA3, were located in previously GWAS-identified breast cancer risk loci." (PMID 39468330, 2024). "In this first breast-tissue-based PWAS of breast cancer risk, we found that five proteins (COPG1, DCTN3, LSP1, DDX6, and DNAJA3) were significantly associated with overall breast cancer risk." (PMID 39468330, 2024). "DNAJA3 was significantly coexpressed with PALB2 in breast cancer." (PMID 39468330, 2024). "Moreover, immunohistochemistry studies using breast cancer tissues show that DNAJA3/Tid1 levels are inversely correlated with tumor malignancy and ErbB2 levels through direct interaction with ErbB2 to promote CHIP-mediated proteasomal degradation." (PMID 34948322, 2021). "DDX6 and DNAJA3 both exhibited a negative association with breast cancer risk in this study." (PMID 39468330, 2024). "Notable examples of tumor suppressive JDP include TID1/DNAJA3 that functions in the mitochondrial matrix as an inhibitor of carcinogenesis and mammalian relative of DnaJ (MRJ) that negatively regulates breast cancer malignancy and reduces b-catenin signaling." (PMID 24278769, 2013).
Alzheimer disease (5 papers, 2021 to 2024). A progressive, neurodegenerative disease characterized by loss of function and death of nerve cells in several areas of the brain leading to loss of cognitive function such as memory and language. "Another mitochondrial protein, DNAJA3 (also known as TID1 or HSP40), is upregulated in the infected neurons, and an increase in DNAJA3 expression is not only associated with increased neuronal apoptosis but also has been shown to be increased in Alzheimer’s disease." (PMID 38002279, 2023).
dilated cardiomyopathy (4 papers, 2014 to 2022). Cardiomyopathy which is characterized by dilation and contractile dysfunction of the left and right ventricles. "Intriguingly, DNAJA3/Tid1 knockout mice develop dilated cardiomyopathy with decreased copy number of mtDNA in cardiomyocytes." (PMID 34948322, 2021). "DNAJA3 has been shown to play a crucial role in preventing dilated cardiomyopathy." (PMID 32149145, 2020).
hepatocellular carcinoma (4 papers, 2020 to 2022). A malignant tumor that arises from hepatocytes. "A recent study in human hepatocellular carcinoma shows that reduced DNAJA3/Tid1 protein levels are associated with increased Nrf2 protein levels and colony-forming potential of human HCC cells, as well as poor clinical outcomes after surgery." (PMID 34948322, 2021).
lung adenocarcinoma (4 papers, 2016 to 2022). A carcinoma that arises from the lung and is characterized by the presence of malignant glandular epithelial cells. "In lung adenocarcinoma, reduced DNAJA3/Tid1 protein levels are correlated with poor overall survival and increased EGFR levels." (PMID 34948322, 2021).
head and neck cancer (3 papers, 2016 to 2021). A primary or metastatic malignant neoplasm affecting the head and neck. "In head and neck cancers, high DNAJA3/Tid1 protein levels are correlated with favorable outcome with reduced malignancy and recurrence by inhibiting the galectin-7-TCF3-MMP9 axis or inhibiting the activities of EGFR and AKT." (PMID 34948322, 2021). "Tid1/Dnaja3, a member of the DnaJ co-chaperone family, has been shown to act as a tumor suppressor in head and neck cancer and non-small cell lung cancer (NSCLC)." (PMID 26919236, 2016).
Ataxia (2 papers, 2021). Ataxia refers to impaired coordination of voluntary muscle movement. "Furthermore, the novel enrichment of neurodegeneration networks among DNAJA3 is compatible with the idea that the ataxia and neuropathy of ClpP-mutant patients are modulated by DNAJA3 accumulation." (PMID 34345994, 2021). "Our novel observation that DNAJA3 shows significantly enriched interaction with disease proteins that are responsible for spinocerebellar ataxia, including the nuclear transcription modulator ATXN1 or the cytosolic stress response factor ATXN3, might be viewed in this context." (PMID 34345994, 2021).
B-cell lymphoma (2 papers, 2022 to 2023). "We used PLA to uncover a close cellular localization of DNAJA3 with MYC in B-cell lymphoma cells." (PMID 36068335, 2022).
diabetes (2 papers, 2023 to 2024). "Taken together, muscular Dnaja3 heterozygosity can induce sarcopenic obesity, impede the blood glucose homeostasis, and raise the risk of diabetes mellitus." (PMID 39132696, 2024).
gastric cancer (2 papers, 2020 to 2021). A primary or metastatic malignant neoplasm involving the stomach. "In human gastric cancer, reduced DNAJA3/Tid1 expression is correlated with a poor prognosis and increased lymph node invasion in patients." (PMID 34948322, 2021). "Indeed, knockdown of DNAJA3/Tid1 in gastric cancer cells increases cell migration and invasion with increased protein stability of galectin-7." (PMID 34948322, 2021).
viral infection (2 papers, 2021 to 2022). "Because S1 is involved in viral invasion, most likely by interacting with yet-to-be identified receptor(s), we hypothesized that DNAJA3 might function on the cell surface by affecting the virus’s entry, either adsorption or internalization, during the viral infection." (PMID 36366511, 2022).
brain tumors (1 paper, 2024). "However, TRAP1 (HSP75), DNAJA3 (TID1), and DNAJC19 remain to be extensively explored in brain tumors regarding their roles in angiogenic dormancy." (PMID 38994941, 2024).
brucellosis (1 paper, 2021). Brucellosis is a bacterial infection that spreads from animals to people via unpasteurized dairy products or by exposure to contaminated animal products or infected animals. "Furthermore, in post-GWAS analysis for mastitis resistance and transcriptome comparative analysis for brucellosis in cattle, the gene DNAJA3 also showed the significant statistical signal." (PMID 33719343, 2021).
colon cancer (1 paper, 2021). "In CRC, increased DNAJA3/Tid1 levels are correlated with colon cancer progression." (PMID 34948322, 2021).
deafness (1 paper, 2021). An inherited or acquired condition characterized by the complete loss of the ability to hear from one or both ears. "These DNAJA3 anomalies are followed by early-onset deafness in ClpP-mutant patients, while a recent report showed anomalies of the mitochondrial matrix chaperone DNAJC30 to occur in hereditary optic nerve atrophy." (PMID 34345994, 2021).
fatty liver disease (1 paper, 2024). A reversible condition wherein large vacuoles of triglyceride fat accumulate in liver cells via the process of steatosis. "As a result, we observed muscular Dnaja3 heterozygosity mice elevated iWAT and eWAT accumulation in the whole body, speculating that may increase the risk of fatty liver disease, such as myosteatosis, during ageing." (PMID 39132696, 2024).
foot and mouth disease (1 paper, 2021). A viral infectious disease that results in infection in cattle and swine, has material basis in foot-and-mouth disease virus, which is transmitted by contaminated fomites, or transmitted by ingestion of food contaminated with infected meat or animal products. "The gene DNAJA3 plays an important antiviral role against foot-and-mouth disease by both degrading VP1 and restoring of IFN-β signaling pathway." (PMID 33719343, 2021).
glaucoma (1 paper, 2020). Increased pressure in the eyeball due to obstruction of the outflow of aqueous humor. "Moreover, we identified Rab5b, App, Stx16, Pikfyve, Dnaja3, Cltc and Dlg4 as key genes impacting glaucoma pathogenesis by transcription differences." (PMID 33133146, 2020).
hyperglycaemia (1 paper, 2024). "To determine whether muscular Dnaja3 heterozygosity would deregulate systemic glucose metabolism and cause hyperglycaemia, we assessed glucose homeostasis with glucose tolerance and insulin tolerance tests, respectively." (PMID 39132696, 2024). "Furthermore, we demonstrated the escalated risk of hyperglycaemia and insulin resistance in aged Dnaja3 heterozygosity mice." (PMID 39132696, 2024).
Insulin resistance (1 paper, 2024). Increased resistance towards insulin, that is, diminished effectiveness of insulin in reducing blood glucose levels. "In our study, we observed the increased protein level of ACC2 in young Dnaja3 heterozygous mice, whereas Dnaja3 haploinsufficiency caused fat accumulation to lead to insulin resistance at aged mice." (PMID 39132696, 2024).
liver cancer (1 paper, 2021). An epithelial or non-epithelial malignant neoplasm that arises from the liver. "Next, to verify the correlation of mRNA expression between DNAJA3 (encodes Tid1) and NFE2L2 (encodes Nrf2) genes, we downloaded the published liver cancer cohort from the Oncomine database and performed Expression Correlation analysis." (PMID 33406664, 2021).
metabolic syndrome (1 paper, 2024). A cluster of metabolic risk factors for CARDIOVASCULAR DISEASES and TYPE 2 DIABETES MELLITUS. "In summary, these findings facilitate the novel therapeutic strategies of GMI via activating DNAJA3 to promote mitochondrial homeostasis and subsequently to mediate muscle function enhancement, metabolic syndrome amelioration and sarcopenic obesity resistance." (PMID 39132696, 2024).
Obesity (1 paper, 2024). Accumulation of substantial excess body fat. "Muscular Dnaja3 haploinsufficiency dysregulates mitochondrial function and lipid metabolism then leads to sarcopenic obesity." (PMID 39132696, 2024). "Moreover, previous study has validated that DNAJA3 mutation is highly associated with waist‐to‐hip ratio adjusted for body mass index (WHRadjBMI) indicating DNAJA3 polymorphism may be highly related to obesity." (PMID 39132696, 2024). "This paradox may indicate the reason why muscular Dnaja3 heterozygosity, impairing mitochondrial function, subsequently leading to sarcopenic obesity and extended survival." (PMID 39132696, 2024). "We observed that the Dnaja3 heterozygosity impaired the mitochondrial homeostasis, which prompts us to further monitor the pathophysiological effects in mediating the sarcopenic obesity in the HSA‐Dnaja3f/+ mice during ageing." (PMID 39132696, 2024). "GMI emerges as a therapeutic regimen for sarcopenic obesity treatment through DNAJA3 activation." (PMID 39132696, 2024). "This study aims to elucidate the physiological effects of muscular Dnaja3 haploinsufficiency on mitochondrial dysfunction and dysregulated lipid metabolism and to assess the efficacy of GMI in rescuing sarcopenic obesity both in vitro and in vivo." (PMID 39132696, 2024).
pancreatic cancer (1 paper, 2022). "Six genes, EARS2, ARL6IP1, DNAJA3, KNOP1, RPUSD1, and TMEM186, significantly coexpressed with PALB2 in both breast and pancreatic cancer." (PMID 35779338, 2022).
tumor (22 papers, 2010 to 2024). "Tid1 (DNAJA3) is an example of HSP40 member that is tumor suppressor in nature." (PMID 28914774, 2017). "An upregulation of TRAP1, DNAJA3, and DNAJC19 genes is observed across different cancers, offering anti-apoptotic signals to maintain and sustain tumor dormancy." (PMID 38994941, 2024). "All six amplifications that led to a substantial increase in expression in tumor samples were also reported as up-regulated HSP when comparing normal and tumor tissues (CCT3, HSPA6, DNAJA3, TRAP1, DNAJC5, and DNAJC5B)." (PMID 38816397, 2024). "The Basal subtype showed the highest number of specific upregulated genes (DNAJC2, DNAJC6, HSPA5, HSPA14 and CRYAA), DNAJA3 and CCT2 were upregulated in Luminal B, and DNAJB3 was only upregulated in HER2 tumours." (PMID 29954368, 2018). "Previous studies show that HSP members are implicated in tumorigenesis, including tumor suppressors HLJ1 (DNAJB4), Tid1 (DNAJA3), DNAJC25, radio-resistance factor HDJ2 (DNAJA1) and other tumor-related members such as DNAJB6, DNAJC12, DNAJC1, DNAJC12, DNAJC15." (PMID 24658033, 2014).
cancer (14 papers, 2010 to 2024). A tumor composed of atypical neoplastic, often pleomorphic cells that invade other tissues. "In addition, DNAJA3 has been reported to play a vital role in sustaining a distribution of mitochondrial membrane potential and the integrity of mtDNA in cancer cells." (PMID 39132696, 2024). "Thus, the roles of DNAJA3/Tid1 in cancer suppression or progression appear to be dependent on the type of cancer and the presence of the variants." (PMID 34948322, 2021). "Furthermore, a study that characterized HSP based on the thematic hallmarks of cancers found a surge in the TRAP1 (HSP75), DNAJA3 (TID1), and DNAJC19 (HSP40 C19 member) (HSP40 family proteins) genes across different cancers, proffering anti-apoptotic signals." (PMID 38994941, 2024). "Surprisingly, expression of DNAJA3 and NFE2L2 mRNA was positively correlated in both normal and cancer tissues in cohort GSE15420, and the correlation coefficient R reached 0.48 with a p value of 1.7 × 10−13 in normal tissues, and in cancer tissues, the R reached to 0.22 with a p value of 0.0015." (PMID 33406664, 2021). "We have extended our investigation by evaluating the role of all human DNAJAs (DNAJA1, DNAJA2, DNAJA3, and DNAJA4) in the response of cells to cancer therapeutic agents, such as doxorubicin, cisplatin, and etoposide, and to define cytotoxic stresses such as ROS and heat shock." (PMID 32149145, 2020).
metabolic disorders (1 paper, 2024). "Moreover, muscular Dnaja3 heterozygosity induced metabolic disorders to increase the risk of pathogenesis of sarcopenic obesity." (PMID 39132696, 2024).
nervous system diseases (1 paper, 2021). "However, despite no detection of LCN2 in the neurons of LCN2-KO mice, we speculate that Dnaja3 is likely an important mediator of LCN2-induced apoptosis in nervous system diseases." (PMID 34903175, 2021).
DNAJA3 also shares sentences with these, for which no sentence is quoted: head and neck squamous cell carcinoma (5 papers); lung carcinoma (5); osteosarcoma (4); muscular dystrophy (3); neurodegenerative disease (3); non-small cell lung carcinoma (3); Parkinson disease (3); colorectal cancer (2); glioma (2); lymph node metastasis (2); muscular disorders (2); autosomal recessive spastic ataxia (1); breast invasive carcinoma (1); cardiomyopathies (1); Cirrhosis (1); developmental delay (1); glioblastoma (1); HIV-1 infection (1); hypertrophy (1); infection (1); lactic acidosis (1); leukemia (1); mastitis (1); Moyamoya disease (1); neuropathy (1); oral cancer (1); ovarian carcinoma (1); peripheral neuropathy (1); renal cell carcinoma (1); schizophrenia (1).
A further 1 disease shares a sentence with DNAJA3 in 1 paper.